CTSB (cathepsin B)
Diseases named in the same sentence as CTSB in open-access papers (continued):
Sharing a sentence is not in itself a finding about the gene and the disease.
glioma (continued). "It has been reported earlier that downregulation of cathepsin B can induce apoptosis by suppressing Bcl2 expression and activating BAX accompanied by alternation in mitochondrial membrane potential in human glioma cells." (PMID 24667798, 2014). "ETS-1 protein is not only differentially expressed in astrocytes and astrocytoma cells but also regulates various targets such as Egr-1, cathepsin B and the urokinase-type plasminogen activator besides PP2A-Aα in gliomas." (PMID 19750005, 2009). "Indeed, simultaneous inhibition of MMP9 and CTSB, both downregulated in miR-7 overexpressed GBM tumors, has already been explored as a potential glioma treatment." (PMID 40813676, 2025). "The proteolytic cascade inhibits GBM cell invasion, which indicates that cathepsin B may be able to regulate the expression of VEGF by regulating the uPA system, and affect the angiogenesis of glioma." (PMID 37398678, 2023). "To confirm these findings, we overexpressed CTSB in glioma cells with and without ar-turmerone treatment." (PMID 37768200, 2023). "Glioma-related studies have shown that lysosomal peptidases are not regulated upstream of TNF-α, and, in gliomas, TNF-α activates cathepsin B/D to mediate cell necrosis, causing RIP1 and RIP3 kinases–driven necroptosis." (PMID 37398678, 2023). "In conclusion, direct or indirect inhibition of cathepsin B activity and the MEOX2-cathepsin S axis in glioma cells may be a direction of future drug research." (PMID 37398678, 2023). "Furthermore, cathepsin B plays a key role in microglial conditioned culture medium (MCM)–induced apoptosis in glioma cells, and nitric oxide is likely the major glioma cytotoxic mediator in microglial conditioned culture medium." (PMID 37398678, 2023). "These miR-637-targeted genes include HMGA1, CDK6, and WNT7A in glioma, HEMGN in PTC, APLN in GC, USP21 in HCC, LY6E and CTSB in CHOL, NUPR1 in OSCC and MM, HDAC4 in SaOS, ABL1 in CML, KLK4 in OC, PLXNB2 in OC, AKT1 in TNBC, PTC, and HCC, AKT3 in TNBC, and RING1 in CCa." (PMID 36175921, 2022). "However, invasive glioma cells express ECM-degrading proteases, such as MMPs, ADAMs, urokinase-type plasminogen activator (uPA), and cathepsin B; invade tissue through complex proteolysis; and remodel the ECM microenvironment." (PMID 35448036, 2022). "These genes include HMGA1 in glioma, AKT1 in glioma, PTC, GC, and HCC, HEMGN in PTC, APLN and MMP19 in GC, WNT1 in CRC, NUPR1 in CRC and OSCC, LY6E and CTSB in CHOL, KLK4 and PLXNB2 in OC, and HDAC4 and STAT3 in SaOS." (PMID 36175921, 2022). "The intra-tumoral distribution of CTSB and LAMP2 nicely paralleled the heterogeneity of p62 and LC3B indicating that central constituents of the ALN are present in similar areas in human gliomas thereby allowing for the functioning of the entire autophago-lysosomal degradation complex." (PMID 26956048, 2016). "Studies of cell survival in glioma show that netrin acts as a pro-survival ligand for UNC5B in glioma as well, while also promoting invasion and angiogenesis of GBM cells by activating RhoA, cathepsin B, cAMP response element binding protein, and Notch signaling." (PMID 34359681, 2021). "This study indicated that cathepsin B may be able to regulate the release of MMP-9 and VEGF, suggesting that the inhibition of cathepsin B will also inhibit tumor growth by inhibiting cathepsin B. Angiogenesis has emerged as a therapeutic approach to inhibiting glioma." (PMID 37398678, 2023). "Yet previous researches about CTSB in gliomas mainly focused on GBM, mostly in vitro, and lacked of comprehensive large-sample clinical analysis, which are inadequate in reflecting the actual role of CTSB regarding the immune microenvironment and tumor heterogeneity of gliomas." (PMID 35277559, 2022).
Alzheimer disease (67 papers, 2009 to 2025). A progressive, neurodegenerative disease characterized by loss of function and death of nerve cells in several areas of the brain leading to loss of cognitive function such as memory and language. "Cathepsin B is a cysteine protease that is implicated in multiple aspects of Alzheimer’s disease pathogenesis." (PMID 37580797, 2023). "CTSB reduced hippocampal amyloid depositions and attenuated learning and memory loss in an Alzheimer’s disease model." (PMID 35884825, 2022). "A previous study demonstrated that CTSB overexpression reduced hippocampal amyloid deposition and attenuated learning and memory loss in a mouse model of Alzheimer’s disease." (PMID 35884825, 2022). "Cathepsins B (CtsB) and D (CtsD) have been found at extracellular sites closely associated to senile plaques in patients suffering from Alzheimer's disease (AD)." (PMID 27902765, 2016). "The majority are only weak inhibitors of human cathepsin B, which has been associated with cancer, Alzheimer's disease and arthritis." (PMID 20920298, 2010). "The abundance of this protein is increased in the brains of individuals with DSAD, which may be associated with a decrease in Cathepsin B activity compared to individuals who have Alzheimer’s disease in the general population." (PMID 39841661, 2025). "Cathepsin B may be a promising candidate for an Alzheimer’s disease diagnostic biomarker." (PMID 38071653, 2024). "For example, a number of studies in mouse models of Alzheimer’s disease found improved brain function following knockout of the CTSB gene." (PMID 39955315, 2025). "Multiple studies on Alzheimer’s disease pathology demonstrated anti-amyloidogenic properties of CTSB or CTSL via direct or indirect enhancement of its enzymatic activity." (PMID 40883786, 2025). "As a case in point, cathepsin B, one of the crucial enzymes involved in the degradation of neurotoxic proteins in Alzheimer’s disease, Huntington’s disease and ALS mouse models, belongs to the LySR network." (PMID 40571723, 2025). "Recent studies have reported that endogenous proteases, including CD10, MMP9, cathepsin D, and cathepsin B, showed fibrinolytic capacity to amyloid-beta fibrils of Alzheimer's disease." (PMID 40302732, 2025). "In Alzheimer’s disease (AD), CTSB exhibits β-secretase-like activity, contributing to amyloid-β (Aβ) production, a key factor in AD pathogenesis." (PMID 39736788, 2024). "For example, clinical findings from multiple studies have shown that CTSB levels are increased in many neurologic conditions, including several neurodegenerative diseases such as Alzheimer’s disease and traumatic brain injury." (PMID 39064733, 2024). "Cathepsin B (CatB) is thought to be essential for the induction of Porphyromonas gingivalis lipopolysaccharide (Pg LPS)-induced Alzheimer’s disease-like pathologies in mice, including interleukin-1β (IL-1β) production and cognitive decline." (PMID 38334675, 2024). "Nonetheless, this study establishes a solid foundation for the rational design of peptide-based inhibitors targeting Aβ oligomers, and underscores the therapeutic potential of APR-derived peptide analogs of Cathepsin B in combating Alzheimer’s disease." (PMID 39858424, 2024). "CTSB levels are elevated in the CSF as well as brain parenchyma of patients with Alzheimer’s disease, and knockout of Ctsb has been shown to ameliorate the neuropathology and behavioral deficits in mouse models of Alzheimer’s disease." (PMID 39118084, 2024). "Cathepsin B (CatB, C01.060) is related to the prototypical papain (C01.001) and is a major drug target, as it is involved in Alzheimer’s disease and various cancer processes." (PMID 37762340, 2023). "We find that the activity of cathepsin B enzyme is decreased in the brain of people who had Down syndrome and Alzheimer’s disease compared with disomic individuals who had Alzheimer’s disease." (PMID 37580797, 2023).
Alzheimer disease (continued). "7B2 precursor, cathepsin B, and heat shock protein 70 were detected as ApKHC1 cargo is involved in Parkinson’s disease, Alzheimer’s disease, polyglutamine diseases, and amyotrophic lateral sclerosis." (PMID 36549915, 2023). "Evidence for participation of the lysosomal cysteine protease cathepsin B (CTSB) in Alzheimer’s disease (AD) memory deficits has been provided by human clinical studies." (PMID 36970896, 2023). "The lysosomal cysteine protease cathepsin B (CTSB) has been suggested as a biomarker for Alzheimer’s disease (AD) because elevated serum CTSB in AD patients has been found to correlate with cognitive dysfunction." (PMID 36970896, 2023). "Levels of several lysosomal proteases including cathepsin D and cathepsin B are increased in CSF and post mortem brain tissue of Alzheimer’s disease patients." (PMID 35732154, 2022). "BBB-permeable CTSB inhibitors have been used in many neurological diseases such as stroke, Alzheimer’s disease and Parkinson’s disease." (PMID 35277559, 2022). "CTSB is a lysosomal cysteine protease that regulates the occurrence and development of tumor, liver fibrosis, obesity, Alzheimer’s disease, and other diseases." (PMID 36558960, 2022). "In Alzheimer’s disease (AD) microglia, it was observed that oxidative stress is crucial in the activation of cathepsin B, a cysteine protease which is believed to play a role in both NLRP3 inflammasome activation and neuronal death." (PMID 35216110, 2022). "Cathepsin B is also an amyloid precursor protein secretase, and inhibition of it has been reported as a potential therapeutic for Alzheimer’s disease." (PMID 31230729, 2019). "In this work we analyzed how inhibition and/or loss of the major lysosomal proteases, the cysteine cathepsins B and L (CtsB/L), affects lysosomal function, cholesterol metabolism and degradation of the key Alzheimer's disease (AD) proteins." (PMID 27902765, 2016). "PADK administered systemically in a mouse model of Alzheimer's disease increased cathepsin B expression and activity, and resulted in the clearance of amyloid beta within neurons." (PMID 24924335, 2014). "In another study in an Alzheimer’s disease mouse model, small-molecule inhibitors of cathepsin B decreased β-amyloid levels and improved memory performance." (PMID 22693552, 2012). "Two of these genes, NEIL2 and MSRA, are related to repair of oxidative damage, and CTSB has been suggested to play a role in Alzheimer's disease." (PMID 20011547, 2009). "While initial studies highlighted potential neuroprotective effects of CTSB, such as reducing amyloid-beta levels and improving cognition in Alzheimer’s disease models, recent evidence suggests its role may extend to promoting neurodegeneration [1097, 1098]." (PMID 40407975, 2025). "However, despite high levels of cathepsin-B have been demonstrated in individuals with Alzheimer's disease, the role of exercise training on its level is less clear." (PMID 38961824, 2024). "Cathepsin-B plays a role in intracellular proteolysis, is associated with an increased risk of cardiovascular events in patients with CAD, and has a neuroprotective role in Alzheimer’s disease." (PMID 38961824, 2024). "In Alzheimer’s disease, accumulation of fibrillar peptide amyloid-β after phagocytosis releases cathepsin B that is sensed by NLRP3 (and at a lesser extent NLRP1) and induces activation of NLRP1 and 3 inflammasomes, which in turn have been found to worsen Alzheimer’s disease patient conditions." (PMID 38644450, 2024). "In addition, CTSB has been considered to protect ß-amyloidosis (Aβ) and cognitive function in Alzheimer’s disease models." (PMID 37299522, 2023). "In humans, the cysteine protease CTSB, besides being reported as a potential risk gene for sporadic PD, has also been implicated as a causative factor for the development of Alzheimer’s disease through incomplete proteolytic processing of amyloid precursors." (PMID 36835737, 2023).
Alzheimer disease (continued). "Similarly, a link has been found between CTSB and the microglia of Alzheimer’s disease and amyotrophic lateral sclerosis in mice." (PMID 36211348, 2022). "EX inhibited the phosphorylations MAPKs, nuclear factor κB (NF-κB), myeloid differentiation factor 88(MyD88), cathepsin B. In conclusion, these results suggest that EX may be a potential agent for treating Alzheimer’s disease." (PMID 28582770, 2017). "Increased cathepsin B was observed in the three HIV-infected individuals with Alzheimer’s disease." (PMID 22693552, 2012). "The ubiquitously expressed cystatin C has received more attention in the realm of neurodegenerative diseases, including Alzheimer’s disease, amyotrophic lateral sclerosis (ALS), and MS, for its inhibitory effect on cathepsin B." (PMID 38879499, 2024). "Here we compared the biology of cathepsin B and CSTB in individuals who had Down syndrome and Alzheimer’s disease, with disomic individuals who had Alzheimer’s disease or were ageing healthily." (PMID 37580797, 2023). "This impact of CTSB on both Alzheimer’s disease and PD is no surprise as there is growing evidence that the two conditions, i.e., sporadic PD and Alzheimer’s, share common pathological links including genetic risk factors." (PMID 36835737, 2023). "Furthermore, increased transport to endosomes of proteases, such as cathepsin B and L, coupled with higher expression of CI-MPR, was shown in Alzheimer’s disease." (PMID 32280996, 2021). "Moreover, preliminary data suggest increased expression of cathepsin B in the hippocampus and basal ganglia of post-mortem brain tissue from HIV-infected individuals diagnosed with HAND, Alzheimer’s disease, and other neuropsychiatric disorders." (PMID 22693552, 2012). "Cathepsin B (CathB) is a lysosomal cysteine protease involved in various pathological and physiological processes and is becoming an attractive target for drug intervention in complex diseases like cancer, traumatic brain injury (TBI) and Alzheimer’s disease (AD)." (PMID 40309011, 2025). "Interestingly, several cathepsins, including CTSB, CTSD and CTSL have been implicated in the pathogenesis not only of PD, but also additional neurodegenerative disorders including Alzheimers Disease (AD)." (PMID 39587654, 2024). "However, using an extended and even more recent list of GWAS results from the European Alzheimer’s disease DNA biobank (EADB) project published as preprint reveals several new connections, i.e. for ADAM17 & USP6NL (both miR-129-5p), CTSB & EED (miR-138-5p), and ANK3 & PLEKHA1 (miR-195-5p)." (PMID 36038535, 2022). "Significantly, chemical inhibitors of cathepsin B are effective for improving deficits in TBI and related injuries including ischemia, cerebral bleeding, cerebral aneurysm, edema, pain, infection, rheumatoid arthritis, epilepsy, Huntington’s disease, multiple sclerosis, and Alzheimer’s disease." (PMID 26388830, 2015).
melanoma (45 papers, 2005 to 2025). A malignant, usually aggressive tumor composed of atypical, neoplastic melanocytes. "While cathepsin B is predominantly expressed in melanoma cells, cathepsin L is mainly found in cancer-associated fibroblasts surrounding the invading melanoma cells." (PMID 38474423, 2024). "Cathepsins cover many different types of proteases, but the cysteine based Cathepsin B, and L and aspartic based Cathepsin D, are most associated with an increased in vitro proliferation and progression of melanoma." (PMID 36005056, 2022). "CTSB activity is significantly elevated in a variant of B16 melanoma with tumor cells of high metastatic potential." (PMID 26995190, 2016). "Upregulated expression of Cathepsin B (CTSB) was observed in melanoma samples compared to nevi and normal skin." (PMID 41155412, 2025). "CTSB is abundantly expressed in melanoma and other tumor types, making it an attractive enzymatic trigger for site-specific drug activation." (PMID 41239499, 2025). "Subsequent investigation of lysosomal protease processing revealed that CEP treatment impaired the proteolytic maturation of both cathepsin B and cathepsin D in a concentration- and duration-dependent manner across melanoma cell lines." (PMID 40862710, 2025). "Cathepsin B also acts as a prognostic marker in melanoma, with variable expression in different tumors." (PMID 39312365, 2024). "SPARC stimulates cathepsin B-mediated melanoma invasion through this mechanism using collagen I and α2β1 integrin as mediators." (PMID 37577749, 2023). "In melanoma, serum level of CTSB were significantly elevated in melanoma patients and identified as a prognosis marker for melanoma mortality." (PMID 36132145, 2022). "Overall, the data from this study suggest the role of IVM in the formation of CTSB induced reticular formation when melanoma metastasizes to the lungs." (PMID 36132145, 2022). "Except for the role of CTSB on NETs, it has been identified that cathepsin protease is essential for melanoma progression." (PMID 36132145, 2022). "Aberrant overexpression of CTSB has been reported in invasive and metastatic cancers including breast cancer, melanoma and colorectal cancer." (PMID 36132145, 2022). "After adding different concentration of cathepsin B (12.5, 25, 50, 100, and 200 ug/L) in melanoma cells for 24 h, the cell viability was significantly increased at the dose of 100 and 200 ug/L(P < 0.05, compared to the control)." (PMID 33335896, 2020). "Melanoma cells incubated with 200 ug/L cathepsin B for 24 h, the total apoptotic value of melanoma cells was decreased from 3.82 ± 0.12 to 3.45 ± 0.09% (P = 0.03)." (PMID 33335896, 2020). "Incubated with 20 mg/L CEP for 24 h the expression of cathepsin B was decreased by 67.67 ± 8.17% in melanoma cells." (PMID 33335896, 2020). "Incubated with 10 mg/L CEP for 24 h, the expression of cathepsin B was decreased by 32.12 ± 7.92% in melanocytes and 10.48 ± 1.23% in melanoma cells." (PMID 33335896, 2020). "Melanoma cells incubated with 200 ug/L cathepsin B for 24 h, the cellular activity was increased 12.7 ± 1.59% comparing with the control (P = 0.015)." (PMID 33335896, 2020). "Cellular levels of mature and precursor forms of lysosomal proteases cathepsin A and cathepsin B were unchanged in melanoma cells by ectopic LAMP-2C." (PMID 30211163, 2018). "Similar results have been found for cathepsin A in malignant melanoma and cathepsin B in non-small cell lung carcinoma and in OSCC." (PMID 29618339, 2018). "Sp1 influences invasiveness of melanoma cells by regulating cathepsin B and metalloproteinase MT1-MMP expression." (PMID 26885752, 2016). "Elevated activity of cathepsin B has been shown to increase the malignancy of various neoplasia such as breast cancer, glioma, and melanoma." (PMID 26157794, 2015).